INS (insulin)
Diseases named in the same sentence as INS in open-access papers (continued):
Sharing a sentence is not in itself a finding about the gene and the disease.
type 2 diabetes (continued). "Small pharmacological studies have suggested positive effects on diastolic dysfunction from optimized metabolic control in patients with type 1 and type 2 diabetes in particular by improving postmeal glucose control, insulin resistance and reducing oxidative stress." (PMID 26772807, 2016). "Bistability can be lost leading to insulin insensitivity and type-2 diabetes." (PMID 26930065, 2016). "Insulin insufficiency leads to type 2 diabetes in an increased insulin-resistant state." (PMID 26978400, 2016). "In addition, the approach in the present study affords a useful option for identification of novel insulin secretagogues for treatment of type 2 diabetes." (PMID 27764176, 2016). "This isn't surprising as despite the proven efficacy of insulin in blood glucose control, its level of compliance and/or acceptance amongst patients with type-2 diabetes is still low due to its relatively higher cost compared to oral hypoglycaemic drugs and unpreferred mode of administration." (PMID 27559312, 2016). "Regarding clinical studies, it has been shown that these bioactive compounds may prevent type 2 diabetes development by improving insulin sensitivity." (PMID 27834920, 2016). "The blood concentration of sulfatide has been noted to be lower in patients with type 2 diabetes, so sulfatide might offer a level of protection or improvement in insulin physiology." (PMID 26981544, 2016). "When looked at together, these observations and the present study suggest that analogue insulin may result in optimized postmeal regulation of myocardial perfusion and hence diastolic function in type 2 diabetes." (PMID 26772807, 2016). "Interestingly, low AGE diets can protect against declining insulin sensitivity and the onset of type 2 diabetes in animal models, even in the context of high fat intake and marked weight gain." (PMID 26223897, 2015). "Furthermore, the influence of lupanine on glucose tolerance and insulin sensitivity was tested in an in vivo model for type-2 diabetes mellitus." (PMID 26492234, 2015). "It should also be noted that in insulin-dependent patients with diabetes type 2 and albuminuria, urine Ang2 levels increase while urine Ang1 levels decrease suggesting that the higher levels of Ang2 in our AKI patients cannot be completely explained by a diminished excretion of Ang2." (PMID 26309217, 2015). "Type 2 diabetes can usually be controlled initially with diet and exercise and with antidiabetic drugs such as metformin and sulfonylureas, but many patients eventually need insulin injections." (PMID 25992895, 2015). "It has been recognized that the concerted actions of insulin and glucagon keep plasma glucose levels normal, and that any imbalance in the actions of these molecules can contribute to an increased demand for insulin, impaired glucose tolerance, and persistent hyperglycemia in type 2 diabetes." (PMID 26378455, 2015). "It is interesting to speculate that pioglitazone decreases hepatic and visceral fat in dysmetabolic monkeys like it does in type 2 diabetic patients to increase hepatic insulin sensitivity." (PMID 25954816, 2015). "Moreover, they are also suggested as an adjuvant therapy for patients with type 2 diabetes, supposedly because they elevate plasma gastrin and thereby improve insulin secretion." (PMID 25993003, 2015). "As the CBD vasorelaxant responses were blunted in patients with type-2 diabetes, we carried out RT-PCR in human aortic endothelial cells (HAECs) to establish the effects of a high glucose (25 mM) or high insulin (500 nM) environment on the expression of the relevant target sites at the RNA level." (PMID 26092099, 2015). "However, type 1 or type 2 diabetes develops when circulating insulin levels drop below the threshold that marks the body's minimum requirements for glucose homeostasis." (PMID 27019722, 2015). "It remains unknown whether the effect of BCAA on insulin induction could have detrimental effect on type 2 diabetes or even pre-diabetic patients." (PMID 26666738, 2015).
type 2 diabetes (continued). "Insulin gene expression and insulin secretion decrease as type 2 diabetes progresses." (PMID 25658116, 2015). "If light therapy effectively improves mood and insulin sensitivity in type 2 diabetes patients with a major depressive episode, light therapy may be a valuable patient friendly addition to the currently available treatment strategies." (PMID 26204994, 2015). "It was somewhat stronger predictor of incident type 2 diabetes compared to fasting insulin." (PMID 25853252, 2015). "In the present study, the insulin concentration under this treatment peaked at 64% of the blank control value, suggesting that β cells still performed the function of insulin secretion to a certain extent, which is similar to the clinical symptom of type 2 diabetes patients." (PMID 25954750, 2015). "Our results indicated that FTO affect the insulin secretion in pancreas islet cells and this may contribute type 2 diabetes occurrences." (PMID 26018652, 2015). "Therefore, we recommend basal insulin use as a safe method in achieving the individualised target of metabolic control in type 2 diabetes patients." (PMID 26176017, 2015). "We also have to consider volunteer bias, since those patients who choose to participate may not be representative of the population of patients we are seeking to treat (ie, those with type 2 diabetes in need of insulin titration)." (PMID 25794243, 2015). "Given the importance of EPAC2 in insulin secretion, a small-molecule EPAC2 agonist may be an effective tool in promoting insulin secretion in type 2 diabetes (T2D)." (PMID 25744542, 2015). "Increased pancreatic GLP-1R expression and circulating GLP-1 levels were also found in insulin-resistant mice with high-energy diet suggesting adaptive response of pancreatic paracrine and endocrine GLP-1/GLP-1R system in insulin-resistant animals with type 2 diabetes." (PMID 25893200, 2015). "Several studies have revealed a reduction in skeletal mitochondrial mass in obesity and type 2 diabetes, decreased ATP synthesis in insulin resistant offspring of patients with type 2 diabetes and decreased maximal respiration rates in skeletal muscle isolated mitochondria from type 2 diabetics." (PMID 26834644, 2015). "However, many patients with type 2 diabetes lose β-cell function over time and require insulin for glucose control." (PMID 25621692, 2015). "In summary, clinical and experimental studies have shown that the inhibition of Ang II by ACE inhibitors or ARBs or antioxidants improve insulin sensitivity and glycemic control in diabetic patients and animals and reduce the incidence of new onset type 2 diabetes." (PMID 25928697, 2015). "It is unknown whether S1P activation influences both type 1 and type 2 diabetes outcomes such as mechanism of β-cell death or insulin resistance in skeletal muscle." (PMID 25866760, 2015). "Moreover, PDX-1 is required in adult humans to promote normal glucose sensing and insulin secretion, and mutations in PDX-1 represent a risk factor for type 2 diabetes." (PMID 26082830, 2015). "Metformin instead of conventional insulin might be an alternative, effective, and cheap treatment option for women with type 2 diabetes in pregnancy in our population." (PMID 25874236, 2015). "In type 2 diabetes, the gradual erosion of beta cell function leads to increased hyperglycaemia while the resistance to the action of insulin could lead to hyperinsulinaemia." (PMID 26193295, 2015). "The authors suggest that insulin-sensitizing agents such as PPARγ agonists may have direct beneficial effects on podocytes of individuals with type 2 diabetes." (PMID 27123439, 2015). "In 1582 SAPHIR participants without type 2 diabetes, we observed nominal associations of rs7578326 with fasting insulin levels and HOMA-IR (P < 0.05)." (PMID 26090471, 2015).
type 2 diabetes (continued). "Consequently, a large number of animal and human studies have observed OP pesticide exposure to be associated with significant increases in plasma glucose, insulin, insulin resistance, and incidence of type 2 diabetes." (PMID 26366294, 2015). "Only one study comparing insulin users versus non-insulin-users showed a statistically significant decreased risk of breast cancer (HR 0.86; 95 % CI 0.81, 0.91) in patients with type 2 diabetes." (PMID 26242987, 2015). "Although, almost all proteins could be targets for glycation, but more specifically, concurrency of hyperglycemia and hyperinsulinemia in type 2 diabetes makes insulin prone to be glycated to generate ROS and produce insulin-AGEs." (PMID 26311627, 2015). "We showed that i.j. glucose elicited greater incretin and insulin release than i.d. glucose in healthy males, supporting the concept that directing nutrients more distally in the small intestine could ameliorate type 2 diabetes." (PMID 25985092, 2015). "This real-world study shows that the odds of having a documented hypoglycaemia was higher in type 2 diabetes patients who initiated a conventional therapy (CT) with premixed insulin or were started on short acting insulin (SIT) than in those who began a basal insulin supported oral therapy (BOT)." (PMID 25698911, 2015). "The ability of AT to enhance glucose uptake in insulin-resistant adipocytes, in addition to its anti-adipogenic effects, suggests that this extract could be useful in the treatment of type 2 diabetes." (PMID 25652009, 2015). "Type-2 diabetes is characterized by insulin resistance and impaired insulin secretion." (PMID 26305241, 2015). "Accordingly, suppressive effect of glucagon by DPP-4 inhibitor may mainly contribute to glucose lowering in longer duration of type 2 diabetes patients with decreased insulin secretion capacities." (PMID 25699116, 2015). "In type 2 diabetes with the increase in the duration of disease a reduction in functional β-cell mass occurs, thus one-third of patients with long disease duration were found to be on insulin therapy." (PMID 26568772, 2015). "On the other hand, some patients in the group who were receiving insulin prior to ICU admission may also have had type 2 diabetes." (PMID 26715333, 2015). "Accordingly, the present study was performed to investigate the role of ziyuglycosides in regulating blood glucose, plasma insulin, and serum lipid parameter levels in db/db mice, a mouse model of diabetes type 2, along with the renal and liver function parameters." (PMID 26198246, 2015). "After secretion, insulin is removed from the plasma by the liver in a process termed insulin clearance, which is altered in obesity and models of type 2 diabetes; the dysregulation of insulin clearance is commonly associated with obesity and type 2 diabetes in humans." (PMID 25822220, 2015). "We here describe the protocol of a study that evaluates the hypothesis that light therapy improves mood as well as insulin sensitivity in patients with a major depressive episode and type 2 diabetes." (PMID 26204994, 2015). "Diabetic ketoacidosis (DKA) is a life-threatening condition that can occur when there is a complete lack of insulin, as in type 1 diabetes, or inadequate insulin levels associated with stress or severe illness in either type 1 or type 2 diabetes." (PMID 26088843, 2015). "Metformin offers a logical alternative to insulin in gestational diabetes and type 2 diabetes in pregnancy as it produces euglycemia by reducing insulin resistance, improving insulin sensitivity, reducing hepatic gluconeogenesis, and increasing peripheral glucose uptake and utilization." (PMID 25874236, 2015). "The insulin sensitizing effects of the PPARγ agonists combined with the lipid-lowering effects of the PPARα agonists would theoretically be efficacious in treating patients with metabolic syndrome or type II diabetes." (PMID 26713088, 2015).
type 2 diabetes (continued). "In obese patients with type 2 diabetes a year after having undergone gastric bypass surgery there was a significant improvement in weight, blood glucose, hemoglobin A1C, and insulin resistance and the percentage of patients with neuropathy was lower than the number of cases at baseline." (PMID 26229968, 2015). "A questionnaire-based study reported that hyperglycemia disrupted driving activities; 8 % of participants with T1DM reported at least one episode of disrupted driving associated with hyperglycemia over 1 year compared with 40 % of participants with insulin-treated type 2 diabetes." (PMID 28702227, 2015). "However, a more recent meta-analysis of GWAS for type 2 diabetes studies in African Americans has found a novel type 2 DM locus near the insulin and IGF2 genes." (PMID 25922844, 2015). "Thus perturbation of insulin signalling in skeletal muscle is a key factor in type 2 diabetes development." (PMID 25866760, 2015). "There is evidence from several randomized controlled clinical trials (RCTs) that the rates of severe and symptomatic hypoglycemia are different among various insulin treatment regimens, favoring long-acting insulin compared to premixed or short acting insulin use in type 2 diabetes." (PMID 25698911, 2015). "Insulin and C-peptide were improved after intervention, which fully reveals that the effect of individualized aerobic exercise intervention on teenagers with type 2 diabetes is remarkable, and it can effectively improve their islet cell function." (PMID 26981161, 2015). "Thus, the aim of the current analysis was to investigate the rates and predictors of documented hypoglycemia in patients with type 2 diabetes on various insulin treatment regimens in general and internal medicine practices." (PMID 25698911, 2015). "Indeed, pathway analysis of the induced genes revealed enrichment of genes participating in insulin secretion and in the development of Type 2 diabetes." (PMID 26330140, 2015). "Early determinants of changes in insulin sensitivity and insulin secretion that precede the development of ectopic fat accumulation could thus facilitate the identification of novel strategies for prevention of type 2 diabetes." (PMID 25723719, 2015). "Plasma insulin levels were assessed to investigate whether hyperglycemia status was accompanied with hyperinsulinemia, the prominent feature of type 2 diabetes." (PMID 26003803, 2015). "During hyperglycemia, the administration of insulin reduced LC3-II levels in type 2 diabetes patient muscle, implying that low levels of insulin may lead to increased LC3-II levels." (PMID 26578885, 2015). "In addition, levels of MMP-9 were reduced after treatment of linagliptin, an inhibitor for dipeptidyl peptidase-4 enzyme to attenuate aberrant biosynthesis and secretion of insulin to treat Type 2 diabetes." (PMID 25859655, 2015). "The current therapies for type 2 diabetes mainly focus on three strategies: i) reducing carbohydrate absorption from the intestine, ii) increasing plasma insulin concentration, and/or iii) improving insulin sensitivity." (PMID 26230680, 2015). "Lower postprandial insulin response may increase insulin sensitivity and decrease low-grade inflammation and is therefore most likely beneficial for the prevention of Type 2 diabetes." (PMID 25826373, 2015). "As hepatic overexpression of Cry1 lowered blood glucose concentrations and improved insulin sensitivity in insulin-resistant mice, molecules able to enhance cryptochrome activity might theoretically be useful to cope with type 2 diabetes." (PMID 25665169, 2015). "For example, Nymphaea stellata extract stimulated glucose-induced insulin secretion and glucose uptake in vitro and insulin response in an in vivo model of type 2 diabetes that was accompanied by increased IRS1 phosphorylation and GLUT4 expression in the liver and muscle." (PMID 26074994, 2015).
type 2 diabetes (continued). "Pump therapy may now be considered as a valuable option in type 2 diabetes patients who fail to respond to an intensified insulin regimen." (PMID 29632572, 2015). "Therefore we carried out this randomized controlled trial to determine the effectiveness of 8-week C. caudatus supplementation on glycemic status and insulin sensitivity in patients with type 2 diabetes." (PMID 26713097, 2015). "As discussed, the sizeable proportion of ICU DKA patients not on insulin at presentation were at greater risk of unfavourable outcomes despite less severe acid–base disturbances, suggesting that the majority had type 2 diabetes." (PMID 26715333, 2015). "Type 2 diabetes represents 90 % of the total cases diabetes mellitus nationwide, and current treatment options range from exercise and diet modification to pharmaceutical interventions that augment insulin sensitivity and alleviate hyperglycemia." (PMID 26336514, 2015). "In this study of 557 patients with type 2 diabetes, microvascular complications were observed in 6 of 18 (33.3 %) patients on diet only, 102 of 341 (29.9 %) patients on oral antidiabetic drugs, and 138 of 198 (69.6 %) patients on insulin treatment." (PMID 26109389, 2015). "In addition, over 6 years of follow-up, two prospective cohort studies with subjects of Asian origin consistently showed a more rapid loss of insulin secretion in LADA, measured as fasting C-peptide, than in type 2 diabetes." (PMID 25572256, 2015). "This is of vital importance in type 1 and advanced type 2 diabetes where the regimen constitutes full insulin-replacement therapy but, in earlier stages of type 2 diabetes, simpler, more convenient regimens may suffice and aid adherence." (PMID 25563978, 2015). "Also, notably before the menopause, obesity and type 2 diabetes, or perhaps the associated inflammation, promote estrogen-independent, notably triple-negative, breast cancer development, invasion and metastasis by mechanisms that may involve macrophage-secreted cytokines, adipokines and insulin." (PMID 26516917, 2015). "Furthermore, insulin release from the beta cell in response to endogenous GLP-1 is preserved in well-controlled type 2 diabetes." (PMID 25811109, 2015). "Interestingly, cardiac mitochondrial function was largely unaffected in the streptozotocin-induced model of type 1 diabetes, which strengthens the insulin-centric paradigm of altered cardiometabolic health with type 2 diabetes." (PMID 26682540, 2015). "Thus, the present study indicates that the potential for salicylate-induced hypoglycaemia should be considered in insulin-treated type 2 diabetes." (PMID 25698911, 2015). "A major limitation of the epidemiology of T1D in adults is certainly the difficulty there is to distinguish it from Type 2 diabetes (T2D) requiring insulin treatment or from Latent Autoimmune Diabetes in Adults (LADA), when specific markers of autoimmunity are not searched." (PMID 25849566, 2015). "Second, MTP expression is increased in insulin-resistant states and type 2 diabetes." (PMID 25725623, 2015). "Moreover, newer anti-diabetic drugs such as incretin analogs and ultra short acting insulin analogs are expensive and hence many patients in the developing world where type 2 diabetes is prevalent cannot afford these medications." (PMID 25722966, 2015). "Additionally, glucose normalisation with insulin treatment also improves β-cell function and the incretin effect in type 2 diabetes." (PMID 26567860, 2015). "A retrospective before-and-after comparison study was performed at a single-site medical center located in the southwestern U.S., comprising 133 Veterans diagnosed with type 2 diabetes receiving insulin therapy with glargine and converted to insulin detemir using a 1:1 unit dosage ratio." (PMID 26120575, 2015).